ENSG00000283877 (novel transcript)
Gene: Protein-coding gene on chromosome 3 (46,581,150 to 46,617,226, forward strand). Ensembl gene ENSG00000283877.
Genetic constraint (gnomAD): Missense variants: 13 observed, 19.67 expected, observed/expected ratio (o/e) 0.66, 90% interval 0.43 to 1.05. Synonymous variants: 6 observed, 8.4 expected, observed/expected ratio (o/e) 0.71, 90% interval 0.39 to 1.4.